PAX6 (paired box 6)
Diseases named in the same sentence as PAX6 in open-access papers (continued):
Sharing a sentence is not in itself a finding about the gene and the disease.
microcephaly (19 papers, 2009 to 2025). A congenital or acquired developmental disorder in which the circumference of the head is smaller than normal for the person's age and sex. "Consistently, compound heterozygous PAX6 mutations are associated with microcephaly in human patients." (PMID 41283518, 2025). "Cases with mutations in both alleles of PAX6 (compound heterozygosity) showed severe brain malformations with obvious microcephaly." (PMID 38094004, 2023). "In this study, I focus on several homeobox genes (ARX, LHX2, MEIS2, NKX2-1, OTX1, OTX2, and PAX6) implicated in the pathogenesis of microcephaly." (PMID 38094004, 2023). "Pax6 plays an important role in the development of the central nervous system and defects in Pax6 expression can cause, for example, microcephaly, which was originally associated with the ADNP-regulator VIP functional deficiency." (PMID 36945042, 2023). "To determine the possible causes of the microcephaly, we examined two major populations of progenitor cells that give rise to all cortical excitatory neurons in the embryonic mouse cortex: PAX6-expressing RGs residing in the VZ and TBR2-expressing IPs residing in the SVZ." (PMID 37612280, 2023). "Furthermore, it has also been demonstrated that in alcohol-induced foetal microcephaly, the abnormality was associated with suppression of Pax6 by ROS, suggesting an interrelation between Pax6 and ROS in vivo." (PMID 24636305, 2014). "In the neocortex, functional loss of Pax6 results in microcephaly which might be induced by an abnormal development of the secondary progenitor population of the subventricular zone (SVZ), also known as basal progenitor cells (BP cells)." (PMID 21073715, 2010). "In the neocortex, loss of Pax6 function results in microcephaly, abnormal development of the secondary progenitor population of the subventricular zone (SVZ, also known as basal progenitor cells, BP cells) and a disproportionate reduction in the production of later-born, upper layer neurons." (PMID 19521500, 2009). "In Pax77 mice, a transgenic mouse model that overexpresses Pax6, expression of both Tbr2 and Tbr1 is increased in the fetal brain, and overproduction of Tbr2-positive cells was observed at E12.5, followed by microcephaly at E14.5." (PMID 33327933, 2020). "Our data also constitute circumstantial evidence linking spindle randomization to the premature differentiation and subsequent depletion of Pax6-positive aNPs, decreased Tuj-1 production and microcephaly in p600SC−/− mice." (PMID 24812355, 2014). "In both cases, altering the levels of Pax6 ultimately leads to microcephaly, but through different cellular and biological pathways." (PMID 19521500, 2009). "Thus, both upregulation and downregulation of Pax6 ultimately converge on a common outcome—microcephaly." (PMID 41283518, 2025). "To study the effect on anterior head structure formation and to determine whether the embryos exhibit normal, mild, or severe microcephaly, we analyzed the development of the eyes (pax6) and cement gland (muc2) by in situ hybridization." (PMID 35372345, 2022). "We observed one single m6A site near the stop codon in 7 microcephaly-related E-SMRs, including Brca2, Cep152, Ddx11, Nde1, Kif14, Stil and Cdk5rap2, 3 polymicrogyria-related E-SMRs (Eomes/Tbr2, Pax6 and Foxp2), and 3 megalencephaly-related E-SMRs (Gli3, Ccnd2 and Kif7)." (PMID 32992647, 2020). "In Hmmrtm1a/tm1amice, however, the predominant phenotype observed was microcephaly, which may be explained by a decreased mitotic rate for Pax6+ radial glial cells; consistent with the recent observations in Hmmrm/m brains, we did observe rare Hmmrtm1a/tm1a brains at E14.5 with cortex enlargement." (PMID 28994651, 2017). "In studies on Zika virus-induced microcephaly, UPR activation was also found to promote direct neurogenesis, and Kira6 treatment could effectively reverse the increase of Nestin and PAX6 positive NPCs." (PMID 39521780, 2024).
microcephaly (continued). "In Pax77 mice, a line of transgenic mice that overexpress Pax6, an increased number of Tbr-positive cells was observed in the neocortex at E12.5, followed by microcephaly at E14.5 with no increase in apoptosis." (PMID 33327933, 2020). "Until today no candidate gene has been reported responsible for such phenotypes: association between congenital cataract, MR and congenital cataract, MR and microcephaly, so we tried to focus on genes already described in ADCC and/or ARCC and expressed in the human brain (PAX6, PITX3 and HSF4)." (PMID 22103961, 2011).
Intellectual disability (17 papers, 2015 to 2025). "Notably, in most previous reports on ASD and intellectual disability, PAX6, TBR1 and FOXP2 were either deficiently expressed or had lost functions." (PMID 31699123, 2019). "Mutations of the human PAX6 gene have also been reported to be associated with autism spectrum disorder (ASD) and intellectual disability." (PMID 35682795, 2022). "It is reasonable to assume that the functional impairment of Pax6, as well as δ-catenin—both of which are expressed in NSCs in the initial stage of cortical development—may cause a severe reduction in neurons in the cortex, resulting in mental retardation or intellectual disability." (PMID 35682795, 2022). "PAX6 and ERLIN2, in the astrocyte module WB.M6, are both implicated in intellectual disability and display co-expression divergence across all cerebral cortex regions." (PMID 33514394, 2021). "There are literatures reporting mutations related with PAX6 gene in patients with ASD, intellectual disabilities, and/or aggressiveness." (PMID 27855195, 2016). "In previous work, we reported the absence of mutations in four genes (PAX6, PITX3, HSF4 and LIM2 genes) encoding for congenital cataract and expressed in the human brain in Tunisian families with cataract and mental retardation." (PMID 37179318, 2023).
iris hypoplasia (17 papers, 2008 to 2025). "We identified two novel mutations within the PAX6 gene in patients with iris hypoplasia and INS." (PMID 32080308, 2020). "Mice heterozygous for a targeted deletion of the Pax6(5a) isoform develop iris hypoplasia and homozygotes have additional minor defects of the iris, retina, lens and corneal stroma but eye size is not reduced." (PMID 27240603, 2016).
congenital cataracts (14 papers, 2013 to 2025). "Mutations in PAX6 were found in two probands, one of them with isolated congenital cataracts (Family 22) and the other one with associated anterior chamber malformations (Family 23)." (PMID 33923544, 2021). "This mutation in PAX6 (G64V) is already reported to cause congenital cataracts with foveal hypoplasia." (PMID 33339270, 2020). "Most genes are associated with isolated congenital cataracts while mutations in the transcription factor genes PAX6, FOXE3, EYA1, MAF, and PITX3 lead to congenital cataract with ASD." (PMID 24555714, 2014). "Disrupting this balance by the overexpression of human PAX6(5a) or mutation in the 5a exon causes an anomalous lens, which can be observed in congenital cataracts." (PMID 23326536, 2013). "In this study, we observed that the heterozygous mutations of PAX6 (c.220A>T/p.Ser74Cys) and WFS1 (c.2070_2079del/p.Cys690TrpfsTer17) were associated with more severe congenital cataracts than the monogenic heterozygous mutation of PAX6 (c.220A>T/p.Ser74Cys) in a Chinese family." (PMID 36843716, 2023). "We believe that this phenotype should be recognized as a new entity within the PAX6 classification, as PAX6-related congenital cataracts." (PMID 34065151, 2021). "Six were congenital cataracts, 10 patients were anterior-segment dysgenesis including PAX6-related phenotype, 48 were retinal dystrophy, and 85 were neuro-ophthalmic condition such as optic atrophy, albinism, or FRMD7-related infantile nystagmus." (PMID 35052368, 2021). "In summary, this manuscript describes the wide phenotypic spectrum of PAX6 mutations, including a newly described phenotype, the PAX6-related congenital cataracts with no iris abnormalities present, and we have also described three new likely pathogenic mutations in the PAX6 gene." (PMID 34065151, 2021). "Further mechanistic investigations are warranted to reveal the interplay between PAX6 and WFS1 in the pathogenesis of congenital cataracts." (PMID 36843716, 2023). "Although several transcription factors such as Pax6, PITX3, HSF4, and HMX1 were allelic with congenital cataracts, MAF family genes are well characterized for the indispensable transcription factor regulating lens development." (PMID 27631609, 2016).
lung cancer (14 papers, 2012 to 2025). A malignant neoplasm involving the lung. "To investigate the effect of PAX6 on lung cancer metastasis in vivo, we established an A549 model of lung metastasis." (PMID 31024010, 2019). "Here, we found that PAX6 expression levels were upregulated in human lung cancer tissues and correlated with poor clinical outcomes." (PMID 31024010, 2019). "To investigate the effect of PAX6 on lung cancer cell metastasis using an in-vivo model, we injected mice with A549 cells expressing si-control, si-PAX6, vector-control, or PAX6-overexpressing lentivirus via the tail vein." (PMID 31024010, 2019). "The current study showed that higher PAX6 expression significantly correlated with reduced duration of OS in lung cancer." (PMID 31024010, 2019). "Low expression of E-cadherin and high expression of PAX6 and ZEB2 were associated with poor prognosis in lung cancer." (PMID 31024010, 2019). "The relationship between PAX6 expression and the expression of lung cancer stem cell biomarkers including CD44, CD133, and ALCAM31 was detected by western blot and immunofluorescence analyses." (PMID 31024010, 2019). "We found that PAX6 expression significantly correlated with the expression of lung cancer stem cell biomarkers in two human NSCLC cell lines." (PMID 31024010, 2019). "To determine if PAX6 can specifically bind the ZEB2 promoter in lung cancer cells, we analyzed binding activity in A549 cells by ChIP assays." (PMID 31024010, 2019). "The PAX6 regulation of cell cycle in lung cancer cells was through the MAPK signal pathway as they found that reduction of PAX6 decreased ERK1/2 and p38 phosphorylation." (PMID 29716531, 2018). "Expression of PAX6 in lung cancer is a somewhat surprising finding, yet it is expected of malignant tumours to show gross aberrations in expression profiles compared to the corresponding normal tissues." (PMID 29568088, 2018). "Although it seems that most studies support an inhibitory role for PAX6 with regard to cell cycle regulation, it is reported that in in lung cancer PAX6 promote cell cycle transition from G1 to S phase." (PMID 29716531, 2018). "In lung cancer PAX6 knockdown cell lines, cyclin D1 is suppressed, indicating that PAX6 promote cell cycle transition from G1 to S-phase." (PMID 29716531, 2018). "PAX6 mRNA levels were significantly elevated in primary lung cancer tissues compared to their matched adjacent tissues." (PMID 24454925, 2014). "The PAX6 mRNA level in 52 pairs of tumors and corresponding matched adjacent normal tissues from non-small cell lung cancer patients and lung cancer cell lines was detected by real-time PCR." (PMID 24454925, 2014). "Similar to pancreatic tumors, PAX6 expression was stronger in lung cancer tissues than in adjacent tissues." (PMID 24454925, 2014). "Pax6 mRNA in lung cancer tissue, as well as matched adjacent tissue, was detected to confirm the role of PAX6 in lung cancer." (PMID 24454925, 2014). "The function of PAX6 in lung cancer cells was evaluated by small interfering RNA-mediated depletion of the protein followed by analyses of cell proliferation, anchorage-independent growth, and cell cycle arrest." (PMID 24454925, 2014). "In this study, we report that increased expression of PAX6 was noted in primary lung cancer tissues." (PMID 24454925, 2014). "In our results, PAX6 mRNA was highly expressed in both lung cancer tissues and lung cancer cell lines." (PMID 24454925, 2014). "It was previously reported that PAX8 and PAX5 are highly expressed in non-small cell lung cancer (NSCLC) and small cell lung cancer cell lines, respectively; but little is known regarding PAX6 expression and function in lung cancer." (PMID 24454925, 2014). "PAX6 expression in lung cancer tissue was higher than that in each matched adjacent normal tissue in all but three cases." (PMID 24454925, 2014). "As PAX6 is frequently expressed in tumors, we determined the PAX6 level in primary lung cancer tissues." (PMID 24454925, 2014).
lung cancer (continued). "In lung cancer cells, PAX6 was shown to promote tumor migration through the PI3K/AKT pathway." (PMID 34989314, 2022). "We further investigated whether PAX6 expression is correlated with the clinical outcome of human lung cancer." (PMID 31024010, 2019). "In parallel, the A549/si-PAX6-injected animals had fewer and smaller tumors than the A549/si-control-injected animals, suggesting that PAX6 expression is critical for the extravasation and invasion of lung cancer cells." (PMID 31024010, 2019). "Importantly, Kaplan–Meier survival analysis showed that lung cancer patients with high-PAX6 expression had shorter OS." (PMID 31024010, 2019). "SMAD3 and PAX6 were upregulated in lung cancer tissues and cancer cells." (PMID 30594196, 2018). "Based on these findings, inhibiting SMAD3 and PAX6 should be further explored and may become a promising mechanism for treating nonsmall cell lung cancer in the future." (PMID 30594196, 2018). "This suggests that PAX6 is a new potential target in lung cancer." (PMID 24454925, 2014). "The PAX6 mRNA was highly expressed in lung cancer tissue and lung cancer cell lines." (PMID 24454925, 2014). "In our study, the function of PAX6 in lung cancer cells was investigated." (PMID 24454925, 2014). "That is to say, in most cases, PAX6 was mainly expressed in lung cancer tissues." (PMID 24454925, 2014). "We also focused on the role of PAX6 in regulating cell cycle progression in lung cancer." (PMID 24454925, 2014). "Our data suggests that PAX6 is a new potential target in lung cancer." (PMID 24454925, 2014). "And PAX6 was highly expressed in lung cancer tissues and lung cancer cell lines." (PMID 24454925, 2014). "Our findings also reveal that PAX6 implicates an oncogenic function in lung cancer." (PMID 24454925, 2014). "All these findings demonstrated that PAX6 functioned as an oncogenic factor in lung cancer." (PMID 24454925, 2014). "It is tempting to speculate about the role of PAX6 in the lung cancer line A2C12, and whether this factor was also recruited." (PMID 22701659, 2012). "Notably, PAX6 is an important transcription factor in humans; however, the molecular mechanism through which PAX6 regulates lung cancer metastasis remains unclear." (PMID 31024010, 2019). "Thus, SMAD3 promotes the progression of nonsmall cell lung cancer by upregulating PAX6 expression." (PMID 30594196, 2018). "However, the regulatory mechanism of PAX6 in lung cancer is still unclear." (PMID 24454925, 2014). "However, little is known about the role of PAX6 in lung cancer." (PMID 24454925, 2014). "An oncogenic role for PAX6 was previously reported for different cancer entities including CRC, breast, and non‐small cell lung cancer." (PMID 40066744, 2025). "Encouragingly, we also found this TUBB3+CD68 TAM subset in a 10× scRNA-seq dataset of human non–small cell lung cancer (NSCLC) biopsy with strong expression of neuronal genes including BMP7, SHANK, CHL1, and PAX6." (PMID 36206343, 2022). "In conclusion, this study reveals a novel link between the binding of PAX6 to the promoter region of ZEB2 and lung cancer progression." (PMID 31024010, 2019). "So that we suppose that PAX6 activates MAPK signaling and promotes cell cycle progression via MET gene transcription in lung cancer." (PMID 24454925, 2014). "PAX6 mRNA was frequently expressed in lung cancer tissue as compared to corresponding adjacent non-neoplastic tissue." (PMID 24454925, 2014). "As a result, cyclin E expression was not affected by the stable shRNA-mediated knockdown of PAX6 in lung cancer cells (data not shown)." (PMID 24454925, 2014). "However, total PI3K (t-PI3K) and total AKT (t-AKT) levels were not changed, indicating that PAX6 can activate PI3K/AKT signaling in lung cancer." (PMID 31024010, 2019).
albinism (13 papers, 2014 to 2024). A congenital disorder characterized by partial or complete absence of melanin pigment in the eyes, hair, or skin. "Disruption of this developmental process results in fovea plana (also called foveal hypoplasia) which can be associated with conditions such as albinism, PAX6 mutations or can occur in isolation." (PMID 38969668, 2024). "Most patients with albinism are reported to have grade 3 FH, but FH is also a characteristic feature of PAX6 mutations, achromatopsia, isolated FH and prematurity." (PMID 31738774, 2019). "Given that hypomorphic albinism is a difficult cohort to diagnose clinically, evidenced by the PAX6 mutation found in the atypical case (proband 9), further exome-seq is suitable for the genetic diagnosis." (PMID 28667292, 2017). "In addition, more variability in grade of foveal hypoplasia is seen in patients with albinism and PAX6 variants compared to SLC38A8 patients, who have a more severe retinal phenotype indicating an earlier arrest in foveal development." (PMID 33498813, 2021). "However, the foveal hypoplasia was not prominent in comparison with inherited developmental retinal disorders such as albinism, PAX6 mutations, and achromatopsia." (PMID 26268155, 2015). "FH has been described in various ocular conditions, including albinism, mutations in genes such as SCLC38A8, PAX6, FRMD7 and AHR and achromatopsia." (PMID 37762234, 2023). "A multicentre study of 907 patients with FH found that 67% of individuals had albinism caused by variants in GPR143, OCA2, TYR and HPS1 genes, followed by 21.8% with PAX6, 6.8% with SLC38A8 and 3.5% with FRMD7 variants." (PMID 37762234, 2023). "Foveal hypoplasia is typically associated with inherited developmental retinal disorders such as albinism, PAX6-related phenotypes and achromatopsia." (PMID 24688117, 2014). "Unlike other disorders (such as albinism or PAX6 mutations) which exhibit a spectrum of foveal hypoplasia, SLC38A8 mutations have arrest of retinal development at an earlier stage resulting in a more under-developed retina and severe phenotype." (PMID 32744312, 2020). "The genes identified for MAC were KMT2D, MAB2IL2, ALDH1A3; ASDA were KERA, PAX6, MYOC, TGFBI, and SLC4A11; congenital cataract were CRYBB2, EPHA2, HSF4 and BCOR; infantile nystagmus were CACNA1A and FRMD7; and albinism were OCA2, GPR143, HPS6 and SLC38A8." (PMID 32830442, 2020).